PEA15 (proliferation and apoptosis adaptor protein 15)
Description:
Blocks Ras-mediated inhibition of integrin activation and modulates the ERK MAP kinase cascade. Inhibits RPS6KA3 activities by retaining it in the cytoplasm (By similarity). Inhibits both TNFRSF6- and TNFRSF1A-mediated CASP8 activity and apoptosis. Regulates glucose transport by controlling both the content of SLC2A1 glucose transporters on the plasma membrane and the insulin-dependent trafficking of SLC2A4 from the cell interior to the surface.
Synonyms: PED; HMAT1; MAT1; PEA-15; MAT1H; HUMMAT1H; PED-PEA15; PED/PEA15
Tractability: Small molecule: a structure with a bound ligand is known. PROTAC: ubiquitination databases record sites on it; its protein half-life has been measured.
Gene: Protein-coding gene on chromosome 1 (160,205,335 to 160,215,404, forward strand). Ensembl gene ENSG00000162734.
Subcellular location: Cytoplasm
Subcellular location (Human Protein Atlas): Cytosol; Nucleoplasm; Vesicles
Pathways (Reactome):
Signal Transduction: RAF-independent MAPK1/3 activation; RAF/MAP kinase cascade
Gene Ontology:
Molecular function: protein binding
Biological process: negative regulation of D-glucose import; negative regulation of extrinsic apoptotic signaling pathway via death domain receptors; MAPK cascade; regulation of apoptotic process
Cellular component: cytosol; microtubule associated complex; cytoplasm
Genetic constraint (gnomAD): Loss-of-function variants: 0 observed, 12.46 expected, observed/expected ratio (o/e) 0, 90% interval 0 to 0.24. The upper end of that interval is the gene's LOEUF score, 0.24, which puts it in group 1 of 6, group 1 being the genes least tolerant of losing a copy. Missense variants: 77 observed, 168.94 expected, observed/expected ratio (o/e) 0.46, 90% interval 0.38 to 0.55. Synonymous variants: 60 observed, 65.7 expected, observed/expected ratio (o/e) 0.91, 90% interval 0.74 to 1.13.
Homologues: Orthologues: chimpanzee PEA15 (100% identical), dog PEA15 (100% identical), guinea pig PEA15 (100% identical), macaque PEA15 (100% identical), mouse Pea15a (99% identical), pig PEA15 (99% identical), rat Pea15 (99% identical), rabbit PEA15 (92% identical), zebrafish pea15 (78% identical), tropical clawed frog pea15 (72% identical).
Diseases named in the same sentence as PEA15 in open-access papers:
PEA15 is named in the same sentence as 65 diseases in open-access papers, as found by Europe PMC text mining. Sharing a sentence is not in itself a finding about the gene and the disease. The quoted sentences say what the papers report.
diabetes (13 papers, 2011 to 2025). "Over-expression of phosphoprotein enriched in diabetes/phosphoprotein enriched in astrocytes (PED/PEA-15) causes insulin resistance by interacting with the D4 domain of phospholipase D1 (PLD1)." (PMID 23585839, 2013). "PEA15 encodes a phosphoprotein responsible for insulin resistance and diabetes." (PMID 31998361, 2019). "Previous studies demonstrate that changes in expression and regulation of Pea15 are present in several diseases including cancer, diabetes mellitus, cardiovascular disease and, in particular, neurological disorders." (PMID 40595283, 2025). "PEA-15, known as phosphoprotein enriched in diabetes (PED), is connected with cell survival and glucose metabolism." (PMID 36937439, 2023). "Higher levels of expression of PEA15 have been reported in both patients with diabetes mellitus type 2 and in euglycemic patients with impaired insulin sensitivity." (PMID 31998361, 2019). "PEA-15 is overexpressed in diabetes mellitus and can regulate insulin sensitivity and glucose uptake." (PMID 24657708, 2014). "The small scaffold protein PED/PEA-15 is involved in several different physiologic and pathologic processes, such as cell proliferation and survival, diabetes and cancer." (PMID 25489735, 2014). "Significant evidence has also indicated the involvement of PEA-15 and PEA-15-regulated intracellular signalling in several different diseases including cancer, diabetes mellitus, neurological disorders and cardiovascular disease." (PMID 24657708, 2014). "This also resulted in the alternative name for PEA-15 of phosphoprotein enriched in diabetes or PED." (PMID 24657708, 2014). "The genes that formed the negative regulation of the glucose import category (PEA15, SIRT6, LEP, and VIMP), were related to obesity and diabetes in human." (PMID 33850161, 2021). "Thus, considering the different known cellular function of PED/PEA-15 in a chronic disorder such as diabetes, the observation that PED/PEA-15 regulates fibroblast motility may have a significant impact on future investigation of its role in diabetic complications." (PMID 21780113, 2012).
breast carcinoma (11 papers, 2009 to 2024). "We further gauged the importance of AMPK activation and PEA15 Ser116 phosphorylation in its association with FADD in breast cancer cells." (PMID 25096718, 2014). "Low expression of PEA15 is strongly correlated to both miRNA clusters expression in luminal A breast cancer." (PMID 37128318, 2023). "We are investigating as a potential target PEA15 (phosphoprotein enriched in astrocytes), a 15-kDa phosphoprotein that is ubiquitously expressed in breast cancer." (PMID 34241740, 2021). "T-VISA-PEA-15 was found to be highly specific, to selectively express PEA-15 in breast cancer cells, and to induce cancer cell killing in vitro and in vivo without affecting normal cells." (PMID 32102425, 2020). "PEA-15 was also found to be epigenetically silenced through promotor DNA hypermethylation in colorectal, lung, and breast cancer tissues." (PMID 26263999, 2015). "In human breast cancer, PEA-15 is overexpressed in correlation with Akt up-regulation, which was considered to contribute to the resistance to breast cancer cell death." (PMID 26263999, 2015). "The PEA-15 gene is amplified in breast cancer as well as in other cancers, where PEA-15 over-expression confers resistance to abroad range of anti-cancer drugs." (PMID 19539371, 2009). "Therefore, PEA15 is a negative regulator of breast cancer; hence it is downregulated in the secretions of MCF7-miR526b and MCF7-miR655." (PMID 37128318, 2023). "Others have shown that PEA15 overexpression inhibited invasion by binding to ERK, and decreased PEA15 expression levels were observed in metastatic breast cancer cells, suggesting that PEA15 may be a suppressor of metastasis." (PMID 34241740, 2021). "Thus, similar to HMECs, breast cancer cells also showed an increase in AMPK activity and PEA15 Ser116 phosphorylation upon matrix deprivation, suggesting the possible involvement of an AMPK-PEA15 axis in the survival of matrix-deprived breast cancer cells too." (PMID 25096718, 2014). "Thus, these set of experiments highlighted the importance of PEA15 and its phosphorylation at Ser116 in breast cancer sphere formation." (PMID 25096718, 2014). "We next assessed the importance of PEA15 and its phosphorylation downstream of AMPK activation in the anoikis-resistant growth of breast cancer cells." (PMID 25096718, 2014). "For this, we first compared the status of AMPK and PEA15 signaling in MCF7 and BT474 breast cancer cell lines grown as ADH monolayer cultures or as cancer spheres in methylcellulose." (PMID 25096718, 2014). "PEA15 protein is downregulated in both miRNA secretomes, interestingly, in HPA data, no breast cancer tissues showed PEA15 expression, but all three control samples showed low PEA15 expression, supporting PEA15 secretome expression." (PMID 37128318, 2023). "In addition, FOSL1 also mediates the dephosphorylation of proliferation and apoptosis bridging protein 15 (PEA15) by upregulating dual-specificity phosphatase 7 (DUSP7), which increases drug resistance in breast cancer." (PMID 36061185, 2022). "In contrast, increased PEA15 expression was also found to inhibit extracellular signal-regulated kinase (ERK)-dependent functional transcription and proliferation in ovarian cancer and breast cancer cells." (PMID 33246486, 2020).
type 2 diabetes (11 papers, 2011 to 2024). "Other ATF2 target genes BDNF downregulation and PEA15 upregulation are also linked to the development of insulin resistance under glucose stimulation, pathophysiology of type II diabetes mellitus." (PMID 32993798, 2020). "PED/PEA-15 overexpression is considered a common defect in first-degree relatives of type 2 diabetic patients, and is associated with reduced insulin sensitivity in these individuals." (PMID 26263999, 2015). "Overexpression of the gene encoding PEA-15 in skeletal muscle and adipose tissue of type 2 diabetic patients, major sites of insulin resistance, was revealed by gene expression studies." (PMID 24657708, 2014). "In addition to the action on glucose homeostasis, upregulation of PEA-15 has also been implicated in other aspects of type 2 diabetes as well as complications associated with the disease." (PMID 24657708, 2014). "This is of interest because PEA15 is involved in type 2 diabetes and is a recently discovered regulator of adipose tissue expansion." (PMID 39595019, 2024). "Similar to type 2 diabetic patients, mRNA and protein levels of PEA-15 were found to be elevated in omental adipose tissue of women with PCOS compared to matched controls." (PMID 24657708, 2014). "Evidence is now emerging for a potential involvement of PEA-15 in cancer, type 2 diabetes, PCOS, Alzheimer's disease and cardiovascular disease." (PMID 24657708, 2014). "PED/PEA-15 is a small scaffold protein, which modulates signalling pathways relevant to several human disorders such as cancer and Type 2 diabetes." (PMID 25489735, 2014). "In TgPED mice, the increase of PED/PEA-15 levels was comparable to that found in cultured fibroblasts derived from skin biopsies of patients affected by type 2 diabetes, compared to unaffected individuals." (PMID 21780113, 2012). "Increased expression of Ped/Pea-15 has been detected in patients with type 2 diabetes and their first-degree relatives." (PMID 21618539, 2012). "PED/PEA-15 overexpression represents a common feature in skeletal muscle, adipose tissue, and fibroblasts from individuals with type 2 diabetes." (PMID 21780113, 2012). "PED/PEA-15 is a gene overexpressed in several tissues and cell types, including fibroblasts, of a large cohort of patients with type 2 diabetes." (PMID 21780113, 2012). "ATK1 inhibits the expression of PEA15, an overexpressed protein in type II diabetes mellitus, where it may contribute to insulin resistance in glucose uptake." (PMID 32993798, 2020). "Several studies have recently shown a key role for PED/PEA-15 in Type 2 diabetes." (PMID 25489735, 2014). "Furthermore, PED/PEA-15 protein levels negatively correlate to insulin sensitivity in offsprings of Type 2 diabetics." (PMID 23585839, 2013). "Phosphoprotein enriched in diabetes gene product (PED/PEA-15) is an anti-apoptotic protein involved in IR and type 2 diabetes mellitus (T2DM)." (PMID 22112520, 2011). "Phosphoprotein enriched in diabetes gene product (PED/PEA-15), an anti-apoptotic protein involved in type 2 diabetes mellitus (T2DM), is overexpressed in PCOS women, independently of obesity." (PMID 22112520, 2011). "From this information, it can be considered for the analysis if hsa-miR-933 can regulate the overexpressed PEA15, downregulated BDNF, or other ATF2 target genes (PRKACB, GNAS, PRKCE, and MAP4K4) to control type II diabetes mellitus." (PMID 32993798, 2020). "The target genes that were significantly enriched for the development of type II diabetes mellitus in both modules are GNAS, PRKACB, PRKCE, MAP4K4, PEA15, and BDNF." (PMID 32993798, 2020). "A more complete understanding of the contribution of PEA-15 in disease progression as well as further identification of the molecules involved in the signalling pathways could lead to the development of novel pharmacological therapies in the treatment of type 2 diabetes." (PMID 24657708, 2014).
type 2 diabetes (continued). "In different populations of Type 2 diabetics as well as in the first degree relatives of these individuals, PED/PEA-15 was found to be commonly over-expressed in skeletal muscle as well as in white adipose tissues and in peripheral blood leukocytes." (PMID 23585839, 2013). "Our approach delineated that hsa-miR-933 might control the hyperglycemic condition and hyperinsulinism by regulating ATF2 target genes MAP4K4, PRKCE, PEA15, BDNF, PRKACB, and GNAS which can otherwise lead to the development of type II diabetes mellitus." (PMID 32993798, 2020). "However, PEA-15 protein did not gain much traction among the research community until it was identified to affect and regulate several critical cellular pathways that could lead to major diseases, such as cancers and type 2 diabetes." (PMID 26263999, 2015).
ovarian carcinoma (9 papers, 2014 to 2023). A malignant neoplasm originating from the surface ovarian epithelium. "Overexpression of miR-212 in ovarian cancer cells could cause downregulated the expression of PEA15 expression." (PMID 32047549, 2020). "By increasing cytoplasmic localization of activated ERK1/2, PEA-15 prevents tumor cell invasion and proliferation, inhibits tumorigenesis in triple-negative breast cancer, and is associated with prolonged overall survival by inducing autophagy in human ovarian cancer cell." (PMID 26263999, 2015). "Studies have shown that microrNA212-regulated PEA15 promotes the progression of ovarian cancer by inhibiting cell apoptosis." (PMID 37056387, 2023). "We believe that the current understanding of the role played by PEA15 in ovarian carcinoma remains controversial because of its multiple complex functions." (PMID 32047549, 2020). "In this study, the relevance of PEA-15 phosphorylation state for cisplatin sensitivity of ovarian carcinoma cells was examined." (PMID 32102425, 2020). "Based on the analysis of ovarian cancer microarray data from Oncomine, GEO and TCGA databases, we found that mRNA expression of PEA15 was significantly up-regulated in ovarian cancer cells compared to normal tissues." (PMID 32047549, 2020). "Herein the expression of miR212 was down regulated in ovarian cancer tissues and its overexpression decreased the expression of PEA15 in OC cells." (PMID 32047549, 2020). "Taken together, these findings demonstrated that silencing of PEA15 in the ovarian cancer cells suppressed both cell proliferation in vitro and reduced tumorigenesis in vivo." (PMID 32047549, 2020). "In contrast, our research provides a new perspective on the role of PEA15 in ovarian cancer based on large-scale surveys from authoritative databases and subsequent biological experiments." (PMID 32047549, 2020). "Our results show that overexpression of PEA-15AA, a PEA-15 variant that cannot be phosphorylated at Ser104 and Ser116, increases the sensitivity of SKOV-3 ovarian cancer cells to cisplatin." (PMID 32102425, 2020). "Immunochemical assays performed using 171 OC tissue specimens proved that the expression of PEA15 was remarkably positively correlated with the FIGO stage and associated with histologic subgroups of ovarian cancer." (PMID 32047549, 2020). "Further studies should explore the correlation between the phosphorylation status of PEA15 at Ser104 and Ser116 sites and clinic pathological features of Ser104 and Ser116 in ovarian carcinoma." (PMID 32047549, 2020). "In the present study, the expression of PEA15 in ovarian cancer and normal tissues analyzed in several databases and PEA15 was found to be significantly up-regulated in OC tissues compared to normal tissues." (PMID 32047549, 2020). "Then, in clinical specimens, we discovered that PEA15 was highly expressed in ovarian cancer tissues, and patients with PEA15 high expression had the poor survival prognosis." (PMID 33246486, 2020). "In this study, we further detected the expression of ERK and pERK after the expression of PEA15 was knocked down in ovarian cancer cells by western-blot analysis." (PMID 32047549, 2020). "In this study, we also explored the effect of PEA15 on ERK and pERK expression and found that silencing of PEA15 decreased the expression of pERK in ovarian cancer cells, this result is consistent with the findings reported by previous studies." (PMID 32047549, 2020). "Another study showed that knockdown of PEA-15 in ovarian cancer cells resulted in resistance to paclitaxel, a standard chemotherapeutic agent for ovarian cancer." (PMID 26263999, 2015). "PEA-15 is upregulated by E1A resulting in reduced proliferation in ovarian cancer by inhibition of ERK1/2-dependent transcription." (PMID 24657708, 2014).
ovarian carcinoma (continued). "We found that the expression of PEA15 in OC tissues was positively related to the clinical stage and histologic grade of ovarian cancer, indicating that PEA15 might participate in the development of epithelial ovarian cancer." (PMID 32047549, 2020). "Analysis of the relevance of PEA15 expression with clinicopathological features revealed that PEA15 protein expression was differentially expressed (P = 0.012) among the histologic subgroups of ovarian cancer (endometrioid, serous, clear cell and mucinous)." (PMID 32047549, 2020). "Furthermore, ZNF703 played a significant role in promoting cancer gene expression, but this seemed inconsistent with previous studies in which PEA15 was found to inhibit ovarian cancer cell proliferation." (PMID 33246486, 2020). "PEA15 was highly expressed in ovarian cancer in multiple databases." (PMID 33246486, 2020). "In conclusion, non-phosphorylatable PEA-15AA increases cisplatin sensitivity of ovarian cancer cells, suggesting that the phosphorylation status of PEA-15 could be evaluated as a biomarker to predict the responsiveness of ovarian tumours to cisplatin treatment." (PMID 32102425, 2020). "However, a recent study demonstrated that phosphorylated PEA-15 sensitised ovarian cancer cells to a chemotherapeutic agent, suggesting that further investigation of the effect of phosphorylation of PEA-15 in inhibiting tumour development might be warranted." (PMID 24657708, 2014). "But there is also evidences in ovarian cancer that PEA15 was positively correlated with the FIGO stage and cell proliferation was obstructed by knockdown of PEA15." (PMID 33246486, 2020). "PEA-15 is a stage III-specific biomarker; its corresponding gene, PEA15, is involved in cell proliferation and apoptosis, and an ovarian cancer study showed that this gene is a promising target for cancer treatment." (PMID 28984208, 2017).
colorectal cancer (6 papers, 2015 to 2025). A primary or metastatic malignant neoplasm that affects the colon or rectum. "For instance, “PEA15 promotes liver metastasis of colorectal cancer by upregulating the ERK/MAPK signaling pathway” published in Oncology reports was retracted as a result of duplication of image and paper mill." (PMID 38984306, 2024). "Previously, PEA-15 overexpression was found to induce cisplatin resistance and knockdown of PEA-15 was shown to enhance sensitivity to cisplatin in colorectal carcinoma cell line." (PMID 32102425, 2020). "In colorectal carcinoma (CRC), the expression of PEA-15 was reported to be significantly associated with pathological T (pT) stadium, which is defined by the extent of tumor invasion into the colonic wall, suggesting a negative relationship between PEA-15 expression and grade of malignancy." (PMID 26263999, 2015).